TIMP1 (TIMP metallopeptidase inhibitor 1)
Diseases named in the same sentence as TIMP1 in open-access papers (continued):
Sharing a sentence is not in itself a finding about the gene and the disease.
cancer (continued). "Panel A was made of MMP-9 as a member of matrix metalloproteinases (MMPs) that are implicated in cancer invasion and metastasis and TIMP-1 as a kind of tissue inhibitor of metalloproteinases (TIMPs)." (PMID 35222743, 2022). "Accordingly, overexpression of TIMP-1 has been associated with a reduction in tumour growth, cancer cell invasiveness and metastasis." (PMID 35277658, 2022). "Some studies have shown that high expression of PTK2 and TIMP1 is associated with poor progression-free survival in patients with various cancers." (PMID 36158681, 2022). "The DNAm surrogate TIMP-1 component appeared to be the main reason GrimAgeAdj mediated the association between adult pack years and cancer, consistent with past research suggesting TIMP-1 plays an important role in cell proliferation in cancerous tissue." (PMID 35643537, 2022). "On other hand, high levels of tissue inhibitor matrix metalloproteinase-1 (TIMP1) have been associated with poor clinical outcomes in several cancer types." (PMID 35008958, 2022). "For example, an increased degree of TIMP1 expression promotes the in vivo growth of both cancer types and stimulates the accumulation of cancer-associated fibroblasts." (PMID 36146640, 2022). "TIMP-1 released from cancer cells promotes the accumulation of cancer-associated fibroblasts (CAFs) within several cancer types." (PMID 36294681, 2022). "DNAm surrogate TIMP-1 is the only component that significantly mediates the association between adult pack years and cancer risk, explaining about 5% of this total association." (PMID 35643537, 2022). "High TIMP-1 expression is strongly associated with a poor prognosis in almost all known cancer types." (PMID 34781885, 2021). "TIMP1 is a matrix metalloprotease that has been implicated in different types of cancer, and its expression is upregulated upon the activation of the conventional NF-κB pathway." (PMID 34572768, 2021). "TIMP1 is commonly found in cancer cells and is associated with a poor prognosis; TIMP2 inhibits the mitogenic response of human microvascular endothelial cells to growth factors; and TIMP4 is an MMP inhibitor in human platelets." (PMID 33960555, 2021). "It has also been suggested that TIMP-1 interacts with CD63 to activate ERK 1⁄2 kinase which promotes accumulation of cancer-associated fibroblast (CAF) in prostate and colon cancer." (PMID 32466129, 2020). "As previously reported, TIMP1 expression is frequently up-regulated in cancers and its increased expression has been associated with poor prognoses in numerous studies." (PMID 31882975, 2019). "In patients, higher TIMP-1 mRNA expression level has been associated with worse prognosis in various cancers, including NSCLC." (PMID 31443242, 2019). "Association of TIMP-1 with cachexia was observed in several established animal cancer cachexia models including the rat hepatoma cancer cachexia model, Wistar rats bearing subcutaneous Walker256 carcinomas, and CD2F1 mice bearing C26 adenocarcinomas." (PMID 29394913, 2018). "Recent studies reported that the dysregulated activity of TIMP1 was associated with cancer progression." (PMID 29659199, 2018). "Our study puts forward the notion that high TIMP-1 levels, associated with various cancers, modulates miRNA expression." (PMID 29507665, 2018). "The data obtained from the present investigation provide first-time proof for cisplatin-induced TIMP-1 release from NSCLC cells as a specific cancer-associated antiangiogenic action on endothelial cells." (PMID 30344920, 2018). "TIMPs are a family of cytokines (TIMP-1, -2, -3, and -4) that are known as endogenous inhibitors of matrix metalloproteinases and associated with advanced disease in numerous adult cancers." (PMID 29137288, 2017). "High stromal levels of TIMP1 in human cancers were found to promote cancer growth, promote the recruitment of cancer associated fibroblasts and accelerate cancer progression." (PMID 26956475, 2016).
cancer (continued). "TIMP1, which is a kind of soluble protein release by endometrial cells, fibroblasts and cancer cells, has been demonstrated to be associated with poor prognosis for a variety of cancers." (PMID 27644693, 2016). "In clinical studies, high serum levels of TIMP-1 in patients with a variety of cancers have been associated with poor prognosis." (PMID 26366732, 2015). "Other studies have confirmed that other TIMP family members are associated with cancer prognosis, e.g., TIMP-1 and TIMP-3." (PMID 25905787, 2015). "The diagnostic value of TIMP-1 in distinguishing between polyps and cancer was determined by ROC curve." (PMID 29201696, 2015). "High expressions of PAI-1, MCP-1, TNF-α, uPA, VEGF and TIMP-1 have been associated with regional or distant metastasis and poor prognosis in cancer patients." (PMID 25356654, 2014). "In the present study, TIMP-1 cancer cell immunoreactivity was associated with a reduction in mortality but not with a reduction in TTP events (primary endpoint)." (PMID 24884504, 2014). "Recent clinical studies have demonstrated that tissue inhibitor matrix metalloproteinase-1 (TIMP-1) levels are elevated in cancer patient plasma and elevated TIMP-1 levels are associated with worse clinical outcomes." (PMID 24143225, 2013). "One explanation for these associations is that TIMP-1 protects cancer cells against the apoptotic stimuli that consecutively affect the cells." (PMID 23202950, 2012). "For example, increased TIMP-1 levels in human cancer tissues have been associated with poor prognoses." (PMID 20587068, 2010). "It therefore seems paradoxical that elevated expression of TIMP-1 has been associated with more aggressive cancers." (PMID 20459644, 2010). "A kinetic enzyme-linked immunosorbent assay (ELISA) for plasma tissue inhibitor of metalloproteinase (TIMP)-1 was developed in order to examine the potential diagnostic and prognostic value of TIMP-1 measurements in cancer patients." (PMID 10408859, 1999). "In age-stratified models adjusted for sex, smoking, and BMI, elevated TIMP-1 levels were strongly associated with incident cancer in participants aged 55-64 years (HR, 95% CI 6.36, 2.50-16.16) and ≥ 65 years (6.23, 1.67-23.21), and with cancer mortality (29.7, 8.25-106 and 18.4, 3.64-93.6)." (PMID 42162053, 2026). "This marker has already been associated with poor prognosis in many cancers 14, and revealing the association between TIMP-1 and other markers, especially CMCs, could be of great value." (PMID 40535809, 2025). "Here, we show that disease-associated double glycosylation of TIMP-1 might causally and mechanistically be related to the cancer-associated increase of the OST complex expression and activity, typical for cancer progression." (PMID 40345589, 2025). "Given its functions, TIMP1 has been linked to reduced cell invasion and metastasis; however, its overexpression has also been associated with increased cell growth and inhibition of apoptosis, contributing to cancer progression." (PMID 40427104, 2025). "As with CENPA, TIMP1 was associated with poor prognosis in most cancers." (PMID 37213288, 2023). "Collectively, our findings suggest that MM-derived TIMP1 may phenotypically convert fibroblasts, similar to cancer-associated fibroblasts, and that TIMP1 may tune the MM microenvironment to promote its expansion by activating fibroblast invasion capacity." (PMID 36768545, 2023). "In addition, given recently reported sex disparities in the association of Timp1 expression with cancer progression, further exploration of its regulatory role in CAC in mice of both sexes is needed." (PMID 36901742, 2023). "Importantly, the association between TIMP1 and ferroptosis-related genes further supports TIMP1 as a potential target for cancer treatment." (PMID 37842645, 2023). "However, increased expression of TIMP-1 in cancer cells has been also associated with cancer progression." (PMID 38069076, 2023). "High TIMP-1 is generally associated with poor cancer outcomes." (PMID 36551979, 2022).
cancer (continued). "In addition, TIMP1 overexpression or TIMP3 silencing have been linked to cancer progression and poor prognosis in NSCLC." (PMID 35688943, 2022). "Besides, TIMP1 levels were also positively associated with the degree of lymph node metastasis, with the deeper the infiltration of cancer cells, the higher the level of expression of TIMP1." (PMID 35778451, 2022). "TIMP-1 promoted the accumulation of cancer associated fibroblasts and cancer progression." (PMID 31601869, 2019). "However, numerous studies have documented that high blood and tissue levels of TIMP-1 in cancer patients are associated with poor prognosis and decreased survival in many cancers, including NSCLC." (PMID 31443242, 2019). "In addition, TIMP1 functions in the modulation of extracellular matrix remodeling and its expression is associated with cancer progression." (PMID 31404090, 2019). "It has been implicated that TIMP-1 inhibition may suppress cancer stemness via inactivation of NF-κB." (PMID 30486830, 2018). "TIMP1 can also induce cell proliferation and has an anti-apoptotic effect, and its overexpression has been associated with a poor prognosis in several types of cancer." (PMID 29484116, 2018). "However, the exact mechanism by which TIMP-1 released from cancer cells causes inhibition of migration and tube formation of HUVECs remains to be clarified." (PMID 30344920, 2018). "Aberrant glycosylation of TIMP-1 was implicated in cancer progression." (PMID 24015777, 2013). "Interestingly, TIMP1 has been linked to the process of anoikis resistance in different cancer models, enabling the evasion of cell death in the absence of substrate anchorage." (PMID 22811761, 2012). "In addition, Timp1 is upregulated and associated with poor clinical outcome for several cancers." (PMID 32722178, 2020). "We further investigated whether ITGAV or TIMP-1 was associated with cancer stemness." (PMID 30486830, 2018). "Among patients with TIMP1 serum data, there were 164 deaths (27.2%), including 90 cancer deaths, during the 10-year follow-up." (PMID 39789100, 2025). "Collectively, these findings emphasize the contribution of TIMP1 overexpression to the regulation of cancer cell migration." (PMID 40427104, 2025). "TIMP1′s role in cancer has been found to be MMP-independent affecting proliferation, apoptosis, angiogenesis and chemoresistance." (PMID 41002380, 2025). "Multifunctionality of TIMP-1 comprises its antiproteolytic functions (inhibition of disease progression-promoting MMPs) and its cancer-promoting cytokine-like activity via interactions with cell surface receptors." (PMID 40345589, 2025). "The study reveals that in the exposure of the HeLa cell line to cannabinoids, TIMP-1 acts as a mediator, which upregulates the anti-cancer activity of cannabinoids within 12–24 h of inoculation." (PMID 40008130, 2025). "TIMP1 has been proved to be an oncogene in malignant tumors, especially in the proliferation, metastasis, drug resistance, stemness and other processes of digestive tract tumors." (PMID 40687427, 2025). "TIMP1 (Tissue Inhibitor of Metalloproteinases 1) has been studied in the proliferation, drug resistance, and metastasis of malignant tumors." (PMID 40687427, 2025). "Among patients with TIMP1 IHC data, there were 238 deaths (31.7%), including 133 cancer deaths, during the 10-year follow-up." (PMID 39789100, 2025). "Some studies reported about the antimigrative characteristics of cannabinoids on the cancer cell line of HeLa by inducing TIMP-1 through the activation of MMP inhibitors for enhancing the anti-invasive effects." (PMID 40008130, 2025). "The PROMISE score includes seven variables (chemotherapy, radiotherapy, hemoglobin, white blood cell count, C‐reactive protein (CRP), ECOG, and cancer type), in addition to the tissue inhibitor of metalloproteinases 1 (TIMP1) for the biological score." (PMID 40392144, 2025).
cancer (continued). "Consistent with these advantages, our in vivo zebrafish models confirmed TIMP1’s role in promoting cancer cell dissemination, with zebrafish injected with TIMP1-overexpressing cells showing enhanced invasion potential compared to controls." (PMID 40427104, 2025). "The husk extract significantly decreased the levels of MMP9 and increased the tissue inhibitors of metalloproteinase-1 (TIMP-1) in both cancer cell lines." (PMID 41226554, 2025). "In conclusion, our work positions TIMP1 as a pivotal regulator of ferroptosis in PCa, with implications for cancers marked by oxidative stress." (PMID 40185230, 2025). "In particular, this study shows that SCs-derived CCL7 binds to its receptor CCR2 in cancer cells to upregulate the expression of the EMT-related factor TIMP1, while TIMP1 binds to CD63 to enhance the expression of CCL7 in SCs." (PMID 40037534, 2025). "Enhanced SERS signals enabled detection of tissue inhibitor of metalloproteinases-1 (TIMP-1), a protein associated with cancer progression." (PMID 40801693, 2025). "By targeting the highly expressed cytokines (IL‐8, TIMP1) identified, tamoxifen resistance in cancer spheroid can be effectively reversed." (PMID 39805002, 2025). "Tissue inhibitors of metalloproteinases (TIMPs), particularly TIMP1, play multifaceted roles in cancer biology." (PMID 40185230, 2025). "This connection emphasizes the importance of examining the intricate functional interplay of TIMP-1 in HLA expression, given the critical role of early DCs activation in cancer immunity and ICT responses." (PMID 38777826, 2024). "The presence of TIMP-1 also suppresses apoptosis in malignant cancer cell lines, potentially through the CD95 pathway, thereby blocking cell death." (PMID 39329731, 2024). "Despite being considered as secreted endogenous inhibitors of metalloproteinases, TIMP1 was reported to promote cancer progression, but its roles in mononuclear phagocytes remained unclear." (PMID 38408082, 2024). "TIMP1 is secreted by cancer cells, fibroblasts, and endometrial cells, and has been associated with a poor prognosis in a variety of malignancies." (PMID 38742936, 2024). "Metalloproteinase inhibitor 1 (TIMP1) has been implicated in various biological processes, including cancers." (PMID 38172678, 2024). "Growing evidence suggests TIMP1 impacts on various cellular processes and regulates the initiation and progression in a wide range of cancers." (PMID 38770133, 2024). "This was established by correlating the reduction in TIMP levels with increased cancer cell invasiveness, while supplementation with TIMP-1 (2.1 nM) and TIMP-2 (2.5 nM) significantly inhibited the chemerin-induced migration and invasion responses." (PMID 39590835, 2024). "This process can increase the expression of the tissue inhibitor of metalloproteinases-1 (TIMP-1), driving the conversion of normal liver fibroblasts into carcinoma-associated fibroblasts (CAFs), thereby contributing to liver carcinogenesis." (PMID 39585028, 2024). "KB: human epithelial carcinoma, Ct: cycle threshold, TIMP-1: tissue inhibitor of metalloproteinases-1, mRNA: messenger ribonucleic acid." (PMID 38481883, 2024). "TIMP1, termed tissue inhibitor matrix metalloproteinase 1, has been widely studied in various cancers." (PMID 36765702, 2023). "TIMP-1 contributes to cancer progression and pathogenesis in a complex way due to its versatile impact on cellular functions stemming from its two-domain structure." (PMID 37500057, 2023). "High levels of TIMP-1 enhance cancer cell propensity for liver metastasis in murine and human pancreatic, lung, gastric, and ovarian cancers, lymphoma, and fibrosarcoma models." (PMID 37350937, 2023). "Although TIMP1 is a natural inhibitor of MMPs involved in the matrix remodeling during carcinogenesis, it converges toward cancer cell survival by binding MMP9/CD44 complex and mediating PI3K/AKT pathway activation." (PMID 36906579, 2023).
cancer (continued). "Most types of cancer cells overexpress TIMP-1 in relation to normal cells, which would seem to inhibit the neoplastic process." (PMID 37509417, 2023). "We found that the tissue inhibitor of metalloproteinase 1 (TIMP1) is a tumour‐secreted protein with high sensitivity and specificity for aggressive cancer, even at early stages in mice." (PMID 37759102, 2023). "Detailed in vitro analyses showed that JZL184 increased the release of TIMP-1 from lung cancer cells, suppressing vascularization in the cancer environment." (PMID 37443791, 2023). "Transwell invasion assay and the expression changes of cancer metastasis-associated proteins (MMP2/9, TIMP1/2) suggested an enforced impact on cell invasion ability in miR-29c mimics group whereas an impaired effect in Anti-miR-29c group." (PMID 35972581, 2023). "We found that TIMP1 is a tumour‐secreted protein with high sensitivity and specificity for aggressive cancer, even at early stages in mice." (PMID 37759102, 2023). "In cohort 2, HIF-1α, TIMP-1, VEGFA, and Ki-67 expression of surgical lung biopsy cases was representatively increased in the cancer cells underlying IP." (PMID 38012636, 2023). "Among them, TIMP1, LGALS3BP, A2M, AHSG, FN1, HRG, and ITIH4 have been associated with cancer, while CF I, C2, and C4A, have been related to complement activity." (PMID 37685286, 2023). "Cancer cell 2 expressed high levels of mesenchymal/basal-like subtype genes including Lgals1, Fbln2, Timp1, and Areg." (PMID 37998349, 2023). "Here, we demonstrate for the first time an indirect antiangiogenic effect of a MAGL inhibitor and the MAGL substrate 2-AG on endothelial cells mediated via CB1 receptors and increased release of TIMP-1 from cancer cells." (PMID 37443791, 2023). "TIMP1 is produced by several types of cancer cells and is involved in the autocrine proliferation loop." (PMID 36768545, 2023). "Transwell invasion assay and the expression alterations of cancer metastasis-associated proteins (MMP2/9, TIMP1/2) showed an accelerative effect of RP11-79H23.3 siRNA on the metastasis capability of NSCLC cells." (PMID 35972581, 2023). "TIMP1 acts as a promoter of cell proliferation in a wide array of cell types, including granulosa cells, fibroblasts, epithelial cells, carcinoma cells, keratinocytes, and leukemic cell lines." (PMID 37873882, 2023). "Subsequently, we investigated the differential expression of TIMP1 between ccRCC and adjacent carcinoma tissues in TCGA database, finding a significant overexpression of TIMP1 in ccRCC." (PMID 37688768, 2023). "Previous studies showed that high expression of TIMP1 in tissue or blood suggested poor outcomes in various cancers." (PMID 35281807, 2022). "Because of its association with cell survival, cell growth, and tumorigenesis, the TIMP-1 protein has been investigated as a potential biomarker, both alone and as part of a panel, in several other cancer types such as gastric, colorectal, and breast." (PMID 36969742, 2022). "The TIMP1 level is significantly increased in lymphocytes infiltrating the tumors and correlated with cancer progression, particularly in GBM." (PMID 35778451, 2022). "Among them, TIMP1 is a soluble protein that can be released from endometrial cells, fibroblasts, and cancer cells, which are correlated with the prognosis of various cancers." (PMID 36238159, 2022). "TIMP-1 expression is also used as a biomarker to evaluate the prognosis of cancer patients and specifically inhibit the activity of matrix metalloproteinases (MMPs)." (PMID 35402615, 2022). "IL-6, IL-8, monocyte chemoattractant protein-1 (MCP-1) and tissue inhibitor of metalloproteinase-1 (TIMP-1) are responsible for the tropism between CSCs and adipocytes, and help to recruit cancer cells into the surface of the omentum." (PMID 35269636, 2022). "TIMPs, which include TIMP1, are secreted proteins that play a crucial role in cancer progression and invasion." (PMID 35534592, 2022).